EPCAM (epithelial cell adhesion molecule)
Diseases named in the same sentence as EPCAM in open-access papers (continued):
Sharing a sentence is not in itself a finding about the gene and the disease.
cancer (continued). "In addition, EpCAM has been demonstrated as a cancer-initiating cell marker of several solid cancers such as breast, colorectal, and pancreatic cancers." (PMID 24727741, 2014). "Many studies have reported that EpCAM-positive cells in HCC are cancer stem cells." (PMID 24696843, 2014). "Therefore, EpCAM-positive cells did not only have the EpCAM gene but also had the characteristics of cancer stem cells." (PMID 24696843, 2014). "Additionally, EPCAM has been widely explored as cancer biomarker in experimental and observational studies." (PMID 24718422, 2014). "The low median numbers of CTCs detected in HNC patients by the CellSearch test could reflect a true low frequency of CTCs in HNC or may be the result of an intrinsic low expression of the capture antigen, EpCAM molecule, on cancer cells surface." (PMID 25105871, 2014). "EMT-like cellular processes may be important during cancer metastasis, and EpCAM is thus an excellent candidate for therapeutic targeting of epithelial cancers." (PMID 24528603, 2014). "Previously, we reported that EpCAM-positive cells had cancer stem cell (CSC) potency." (PMID 24696843, 2014). "In normal cells, EpCAM appears to be sequestered in tight junctions and is therefore less accessible to antibodies, whereas in cancer cells it is widely distributed on the cell surface and has therefore been explored as a surface-binding site for therapeutic antibodies." (PMID 25265904, 2014). "EPCAM plays an important role in the initiation and progression of cancer." (PMID 24718422, 2014). "EpCAM expression was similar in benign and malignant tumors." (PMID 23251255, 2013). "Taken together, our observation suggests that catumaxomab might have a relevant systemic effect on cancer cells and therefore might improve the prognosis of patients with EpCAM-positive tumors." (PMID 24380380, 2013). "It has, therefore, been speculated that EPCAM on normal epithelia is sequestered and, therefore, much less accessible to antibodies than EPCAM in cancer tissue, where it is homogeneously distributed on the cancer cell surface." (PMID 23938213, 2013). "Furthermore, it has been shown that EpCAM overexpression in cancer cells can support proliferation by enhancing Wnt signaling." (PMID 23758908, 2013). "Here, we addressed a hypothesis that leaky promoter expression can be controlled by introducing miRNA target regulation to restrict the expression of the suicide gene to EpCAM positive cancer cells." (PMID 24391761, 2013). "In both human cancer cell lines knockdown of ZEB1 resulted in elevated EPCAM and CDH1 expression." (PMID 23667256, 2013). "Therefore, in our study we used let-7b miRNAs targets in the 3’UTR region of the EpCAM promoter driven suicide gene to restrict its expression to the cancer cells compared to the normal cells." (PMID 24391761, 2013). "The cancer cells were labeled with α-EpCAM PE antibody, recognizing a human epithelial adhesion molecule and directly conjugated to the fluorochrome PE (red): the corresponding signal was associated with the plasma membrane of the cells adherent to the monolayer." (PMID 23451255, 2013). "Because the increased expression of EpCAM in exosomes has been suggested among patients with certain cancer types, a methodology that differentiates mixtures of exosomes into EpCAM(+) and EpCAM(−) subpopulations is urgently required to develop diagnostic devices that use exosomes." (PMID 26082317, 2013). "Moreover, down regulation of EpCAM is required for cancer cell invasion, which takes place during EMT, a process via which epithelial cells gain mesenchymal characteristics that empowers them to metastasize." (PMID 24305653, 2013). "This led to our investigation of co-expression of PDGFRα and EpCAM using cancer cell lines." (PMID 23990866, 2013).
cancer (continued). "CTCs, originating from carcinomas, normally express epithelial markers such as EpCAM (epithelial cell adhesion molecule) and keratins, on the other hand, CD45 molecules, also known as leukocyte common antigen, are expressed on the surface of white blood cells only." (PMID 24058649, 2013). "Whether EpCAM has a pro- or an anti-tumorigenic function in cancer appears to be dependent on the cancer type." (PMID 23110550, 2012). "Thus, EpCAM can shift from a protective to a promoting role in cancer, depending on the differentiation or dedifferentiation status of epithelial cancer cells." (PMID 23110550, 2012). "This Dox conjugate can be applied as a therapeutic agent in all cancers overexpressing EpCAM." (PMID 23213278, 2012). "The correlation of EpCAM expression and clinical outcome therefore depends on the cancer entity." (PMID 22590529, 2012). "Epithelial cell adhesion molecule (EpCAM) is a transmembrane protein involved in cell adhesion and mitogenic signalling and is frequently overexpressed in embryonic stem cells, cancer initiating cells and human cancers." (PMID 23049733, 2012). "The trifunctional antibody (trAb) catumaxomab (Removab®, Fresenius Biotech GmbH, Munich, Germany) was approved in the European Union in April 2009 for the intraperitoneal (i.p.)treatment of malignant ascites in patients with epithelial cell-adhesion molecule (EpCAM)-positive carcinomas." (PMID 21702044, 2012). "EpCAM was the first target for monoclonal antibody therapy against human cancer." (PMID 22590529, 2012). "The EPCAM gene codes for an epithelial cell adhesion molecule and is overexpressed in most cancers." (PMID 22548175, 2012). "Importantly, EpCAM is apparently needed to maintain distinct cancer cell attributes and, potentially, the cancer stem-cell phenotype." (PMID 22304365, 2012). "EPCAM is a homophilic intercellular adhesion molecule that may prevent metastasis, but conversely EPCAM may also promote metastasis of cancers to prevent intercellular adhesion mediated by E-cadherin." (PMID 22548175, 2012). "EpCAM is a putative cancer stem cell marker and is dysregulated in several epithelial cancers." (PMID 23213278, 2012). "In conclusion, we showed that EpCAM+ RB cells behave like cancer stem cells in vitro." (PMID 22328825, 2012). "Like EpCAM showed variable results in variable cancers, TROP2 may play different roles in different cancers." (PMID 22482828, 2012). "Next, we demonstrated that EpCAM+ cells possess cancer stem cell-like properties." (PMID 22328825, 2012). "Thus, the present data clearly showed that EpCAM is co-expressed with three other cancer stem-like cell markers." (PMID 22328825, 2012). "Our study shows for the first time that EpCAM+ RB cells behave like cancer stem cells." (PMID 22328825, 2012). "In addition, EpCAM is hyperglycosylated to a 40 kDa or 42 kDa isoform in carcinoma tissue as compared with healthy autologous epithelia." (PMID 23110550, 2012). "In addition, metastatic and recurrent tumors were found to express significantly higher levels of EpCAM when compared with primary carcinomas." (PMID 23056490, 2012). "Thus, we developed LNA-modified nucleolin aptamers and LNA-modified EpCAM aptamers conjugated “Fe-bLf natural anticancer protein-loaded nanobullet nanocarriers,” which specifically target cancer cells and spare normal cells." (PMID 21955150, 2011). "However, the expression of EpCAM affected cancer-related signaling molecules in both cell lines and seemed to contribute in triggering complex biological processes, which account for an aggressive tumoural behaviour." (PMID 21281469, 2011). "At none of the time-points, an association was found between EpCAM positivity in blood and/or peritoneal cavity and cancer-specific or disease-free survival." (PMID 21281486, 2011).
cancer (continued). "Unlike genetic mutations, epigenetic mutations are reversible; a better understanding of the regulation of EpCAM gene expression may thus provide new opportunities for cancer therapy, based on reversing epigenetic marks." (PMID 21694727, 2011). "The same methodology was used by other groups for the functional analysis of EpCAM function in EpCAM overexpressing HEK293 cancer cells, where EpCAM positive cells exhibited enhanced proliferative and metabolic activity compared to cells with low or no antigen expression." (PMID 21281469, 2011). "Furthermore, in cancer cells, intracellular domain of EpCAM cleaved by TACE and presenilin-2 accelerates cell proliferation through the activation of β-catenin signaling." (PMID 22194864, 2011). "The approval dates back to April 2009, when the European Commission followed the recommendation of the Committee for Human Medicinal Products (CHMP) and approved catumaxomab for the i.p. treatment of malignant ascites in patients with EpCAM+ carcinomas resistant to standard treatments." (PMID 22235224, 2011). "In this respect, transient siRNA-mediated silencing of EpCAM expression has been shown to reduce the oncogenic potential of breast, gastric, hepatocellular and oral squamous cell carcinomas." (PMID 21694727, 2011). "TROP2, a cell surface protein structurally related to EpCAM, is expressed in various carcinomas, though its function remains largely unknown." (PMID 22194864, 2011). "CTCs enriched from blood of patients with carcinoma were defined as EpCAM+CK+CD45-." (PMID 21595914, 2011). "Epithelial cell adhesion molecule EpCAM is over expressed in cancer initiating cells." (PMID 21317450, 2010). "There is a large database on EpCAM staining for many cancers and normal tissues." (PMID 20579375, 2010). "There are numerous reports in the literature on the cell membrane expression of EpCAM in TC and other human cancers, leading to the suggestion that it could be an ideal candidate for application as a cancer marker and a therapeutic target." (PMID 20579375, 2010). "These numerous reports on the cell surface expression of EpCAM in human cancers have suggested that it could be an ideal candidate for application as an epithelial cancer marker and a therapeutic target." (PMID 21152431, 2010). "A large number of monoclonal antibodies (mAb) against the Epithelial Cell Adhesion Molecule (EpCAM) which is expressed only in epithelium and malignant tumors derived from epithelia have been increasingly used to enrich and isolate CTC from blood and DTC from bone marrow samples." (PMID 20426872, 2010). "The regulated intramembrane proteolysis (RIP) of EpCAM has recently been proposed to produce Ep-ICD that has been shown to transduce EpCAM signaling in cancer cells and activate Wnt proteins-resulting in increased nuclear accumulation of β-catenin and the target genes - c-myc and cyclinD1." (PMID 20579375, 2010). "Epithelial cell adhesion molecule (EpCAM) is frequently and highly expressed on human carcinomas." (PMID 21044305, 2010). "The epithelial origin of this carcinoma was confirmed by its expression of EPCAM." (PMID 20356397, 2010). "The stromal tissue surrounded clusters of cancer cells, which stained with an anti-EpCAM antibody." (PMID 19956597, 2009). "Color FILM using a 10X objective showed the antibody was able to target cancer cells based on expression of the epithelial cell lineage marker EpCAM, while the vascular probe and protease sensor provided feedback on the extent of vascularization and stromal cell infiltration." (PMID 19956597, 2009). "While pan-carcinoma markers, such as EpCAM, should target many cancers, pre-operative biopsies could be used to identify appropriate markers, similar to the indication for trastuzumab." (PMID 19956597, 2009).
cancer (continued). "In addition, CD64 was described as an attractive target molecule for bsAb based immunotherapy of cancer; anti-EpCAM × anti-CD64 bsAb were characterized to mediate strong cytotoxicity in vitro after GCSF and IFN-γ pre-stimulation of PBMC." (PMID 19216794, 2009). "Thus, the aptitude of EpCAM to regulate gene transcription alongside with the Wnt pathway and its strong oncogenic potential pinpoint an important role in cancer, eventually related to the origin of malignancies, i.e. cancer-initiating cells." (PMID 19925656, 2009). "Regulated intramembrane proteolysis (RIP) is mandatory for activation of EpCAM-signalling in carcinoma cells and may represent the basis for the observed decrease of intact EpCAM molecules at the cell surface owing to EpEX shedding." (PMID 19925656, 2009). "Furthermore, EpCAM enhances proliferation rates of carcinoma cells, presumably mediated via direct nuclear signaling of its proteolytically cleaved intracellular domain EpICD, and via c-Myc and the cell cycle regulators cyclin A and E." (PMID 19609345, 2009). "Next, EpCAM cleavage was monitored in carcinoma cells upon dual staining with domain-specific antibodies against EpEX and EpICD in conjunction with distinct fluorescence-labelled secondary antibodies in carcinoma cells." (PMID 19925656, 2009). "Recent evidence is suggestive of EpCAM to serve as a cancer stem cell marker." (PMID 19002182, 2008). "Expression of EpCAM in the cancer cell lines was confirmed by flow cytometry." (PMID 19002182, 2008). "All investigated cancer cell lines expressed EpCAM, as revealed by western blot analysis." (PMID 19002182, 2008). "All these features have encouraged the development of various EpCAM-directed anti-cancer therapies." (PMID 17622246, 2007). "Future research on EpCAM may benefit from a unified nomenclature and more frequent exchange among those who have been working on this cancer target during the past 30 years and will do so in the future." (PMID 17211480, 2007). "Future studies need to investigate and corroborate whether EpCAM is a marker for highly tumorigenic cancer stem cells, as has recently been suggested." (PMID 17211480, 2007). "This demonstrates the suitability of using EpCAM for antibody-based cancer therapy, in principle." (PMID 17622246, 2007). "Moreover, the first monoclonal antibody ever applied for human cancer therapy was murine mAb 17-1A recognising EpCAM." (PMID 17211480, 2007). "The reason of testing EpCAM in UM is the anti-EpCAM drugs avaiable to treat some malignant tumors." (PMID 17125516, 2006). "Recently, EGP-2, also referred to as 17-1A or EpCAM, has been shown to be expressed as a stable transmembrane protein at high levels on a variety of epithelial tissue derived cancers, such as those of the breast, pancreas, gonads, gastrointestinal, respiratory and urinary tracts." (PMID 16457694, 2005). "Therefore, we reasoned that EpCAM-ReTARGTPRIFNαR149A could be an attractive treatment option for this cancer type." (PMID 40243928, 2025). "Additionally, other IFNα-sensitive EpCAMpos cancer types may also be promising targets for EpCAM-ReTARGTPRIFNαR149A therapy." (PMID 40243928, 2025). "A key result from the profiling study showed that exosomal EpCAM and CD24 levels were significantly higher in ovarian cancer patient samples, and pairing these protein profiles increased diagnostic accuracy to 97% for distinguishing cancer from non-cancer controls." (PMID 40801693, 2025). "Our new anti-EpCAM sdAbs may inhibit cancer cell growth by decreasing WNT5B signaling." (PMID 40017594, 2025). "Additionally, the heterogeneity within carcinomas may also be reflected in the EpCAM expression of the CTCs." (PMID 40343949, 2025). "Interestingly, despite the inter‐plasma variations amongst EVs of the same cellular origin, the change of fluorescence polarisation for the detection aptamer against CD63 can demarcate the EVs immobilised with anti‐EpCAM antibody from three different cancer cells." (PMID 39221546, 2024).
cancer (continued). "Moreover, the expression of EpCAM varies in the subtypes of the same cancer." (PMID 38791091, 2024). "In addition, EpCAM is abundantly expressed thus has been studied extensively in many cancer types." (PMID 39010070, 2024). "Consequently, EpCAM has emerged as a promising target for clinical cancer therapy." (PMID 39397869, 2024). "EPCAM is a membrane protein considered in the past to play a role in regulating cellular communication as an adhesion molecule, but now this protein has been shown to have various biological functions, including in the regulation of cell proliferation and cancer stemness." (PMID 39033780, 2024). "Moreover, we exploited a CIBERSORTx digital flow cytometric analysis of NSCLC RNA-Seq bulk tumors, and we identified that immune (CD45+), epithelial/cancer (EpCAM), and stromal (CD10+ and CD34+) subsets were expressed in NSCLC and associated with poor prognoses." (PMID 37509650, 2023). "Additionally, MOC31PE has a competitive edge over earlier anti-EpCAM antibody-based treatments due to its “simpler” mode of action, requiring just binding to EpCAM-expressing cancer cells before directly promoting cancer cell death through toxin release inside the target cells." (PMID 37190310, 2023). "Moreover, ZFX silencing reduces the transactivation of β-catenin in liver EpCAM+ cancer stem cells; however, the detailed mechanism remains unclear." (PMID 37864206, 2023). "CLDN18- and/or EPCAM-expressing epithelial clusters in the Uniform Manifold Approximation and Projection of total cells were further divided into 9 different groups with several undefined clusters, including gastric, intestinal, and dysplastic or cancer cell lineages." (PMID 37196797, 2023). "However, extended studies of the role of EpCam in cancer progression is required before its expression could be attributed to aggressive or non-aggressive tumors." (PMID 36875773, 2023). "The upregulated expression of EpCAM denotes a highly aggressive cancer proliferation due to involvement in the regulation of cellular adhesion, migration, proliferation, cycle metabolism, and metastasis, negatively correlating the EpCAM expression with the expected survival of cancer patients." (PMID 37754116, 2023). "The expression of EPCAM has been found in many types of stem cells, progenitor cells, epithelial tissues, and many types of cancers, and it is considered a multifunctional transmembrane protein, involved in the regulation of the cell stemness, growth, adhesion, and motility of cancer cells." (PMID 36674577, 2023). "Overexpression of EpCAM in multiple malignancies indicates that complementary treatment with EpCAM-targeting agents might be a universal strategy to potentiate the effect of targeted cancer therapy." (PMID 36769161, 2023). "In addition, an EpCAM RNA aptamer-conjugated PEGylated liposomal DOX (ER-lip) was also designed for targeted cancer therapy, which demonstrated that ER-lip could promote the survival of animal models and reduce the tumor growth rate." (PMID 36559056, 2022). "Furthermore, the overexpression of FOXM1 leads to the acquisition of an EMT phenotype by activating the mesenchymal cell markers ZEB1, ZEB2, Snail2, E-cadherin, and vimentin, which are associated with increased spheroid-forming capacity and cancer stem cell surface markers (CD44 and EpCAM)." (PMID 36613925, 2022). "However, there are complicated roles for EpCAM in the different cancers which may be attributed to the fact that the binding partners of EpCAM and the mechanisms by which it signals in and out of the cell are not fully known." (PMID 34240826, 2022). "Therefore, EpCAM is thought to be a promising target for cancer diagnosis and therapy." (PMID 35735360, 2022). "Moreover, EpCAM also regulates the proliferation of cancer cells." (PMID 35159188, 2022). "Furthermore, an EpCAM-aptamer-based platform for specific gene knockdown may be a novel therapeutic approach to overcome cancer resistance and immune evasion." (PMID 36369033, 2022).